MALT1 (MALT1 paracaspase)
Diseases named in the same sentence as MALT1 in open-access papers (continued):
Sharing a sentence is not in itself a finding about the gene and the disease.
chronic lymphocytic leukemia (6 papers, 2017 to 2025). "Instead, it recruits an ITAM-linked FcRγ, which initiates signaling through Syk and likely the Caspase recruitment domain family member 9/B-Cell CLL/lymphoma 10/Mucosa-associated lymphoid tissue lymphoma translocation protein 1 (CARD9/BCL10/MALT1) complex." (PMID 28640912, 2017). "The short tail recruits an ITAM-linked FcRγ, which activates signaling through Syk and possibly the Caspase recruitment domain family member 9/B-Cell CLL/lymphoma 10/Mucosa-associated lymphoid tissue lymphoma translocation protein 1 (CARD9/BCL10/MALT1) complex." (PMID 33628745, 2020). "Safimaltib was recently developed as a specific MALT1 paracaspase inhibitor, and it is currently under early clinical investigation in patients with non-Hodgkin lymphoma and chronic lymphocytic leukemia (ClinicalTrials.gov NCT03900598)." (PMID 36719376, 2023). "MI-2 is an irreversible inhibitor of MALT1, which has been reported effective in chronic lymphocytic leukemia and ABC-DLBCL." (PMID 33072583, 2020). "In addition to ABC-DLBCL, MALT1-dependent activation of the NF-κB transcription factor drives the pathogenesis of multiple other B and T cell malignancies, including subsets of mantle cell lymphoma, adult T cell leukemia, and chronic lymphocytic leukemia with chronic B cell receptor signaling." (PMID 40231473, 2025). "Early-phase clinical trials investigating several MALT1 protease inhibitors in relapsed or refractory B cell non-Hodgkin lymphoma (including DLBCL) and chronic lymphocytic leukemia are under way (ClinicalTrials.gov NCT05618028, NCT03900598, NCT04876092, NCT04657224, NCT05515406, and NCT05544019)." (PMID 40231473, 2025).
experimental autoimmune encephalomyelitis (6 papers, 2014 to 2020). An autoimmune demyelinating disease of the central nervous system that is produced experimentally in animals by the injection of homogenized brain or spinal cord in Freund's adjuvant. "As Malt1-deficiency was shown to protect against the development of experimental autoimmune encephalomyelitis (EAE) despite diminished Treg numbers, we tested whether it could also protect against graft rejection in a skin transplantation model." (PMID 33042160, 2020). "For this, we studied the therapeutic potential of a recently identified inhibitor of MALT1 protease activity, the phenothiazine derivative mepazine, in the context of experimental autoimmune encephalomyelitis (EAE), the main animal model for MS." (PMID 25043939, 2014). "Experimental studies have highlighted that Malt1-deficient mice were resistant to experimental autoimmune encephalomyelitis, although they lacked peripheral regulatory T cells (Treg)." (PMID 33042160, 2020). "CARMA1- or MALT1-deficient mice are fully protected from induction of experimental autoimmune encephalomyelitis (EAE) by immunization with myelin oligodendrocyte glycoprotein (MOG), and treatment of mice with the MALT1 inhibitor mepazine attenuates onset and progression of the disease." (PMID 26507244, 2016).
leukemia (6 papers, 2012 to 2026). A malignant (clonal) hematologic disorder, involving hematopoietic stem cells and characterized by the presence of primitive or atypical myeloid or lymphoid cells in the bone marrow and the blood. "For these reasons, many involved in the development of chemotherapeutic treatments for leukemia view MALT1 as a promising potential drug target." (PMID 33401649, 2021). "Therefore, MALT1-mediated NF-κB activation can be diminished by inhibiting MALT1 proteolytic activity, which is a potential therapeutic approach for the treatment of leukemia." (PMID 33401649, 2021).
Sepsis (6 papers, 2017 to 2025). Sepsis is defined as life-threatening organ dysfunction caused by a dysregulated host response to infection. "Mucosa-associated lymphoid tissue lymphoma translocation protein 1 (MALT1) modulates the inflammatory immune response and organ dysfunction, which are closely implicated in sepsis pathogenesis and progression." (PMID 36960276, 2023). "PBMC MALT1 is highly expressed in sepsis patients with its overexpression associated with multiple organic dysfunctions, elevated Th17 cells, and increased mortality risk." (PMID 35262976, 2022). "In the current study, it was shown that PBMC MALT1 expression was higher in sepsis patients compared with HCs; meanwhile, MALT1 overexpression was linked with high sepsis risk." (PMID 35262976, 2022). "The current study disclosed that the upregulation of MALT1, Th1 cells, Th17 cells, and IL‐17A was correlated with higher mortality risk in sepsis patients." (PMID 35262976, 2022). "Subsequently, MALT1 is linked with mortality risk in sepsis patients." (PMID 35262976, 2022). "Thus, elevated MALT1, together with Th1 cells, Th17 cells, and IL‐17A, is correlated with higher mortality risk in sepsis patients." (PMID 35262976, 2022). "Collectively, PBMC MALT1 is highly expressed in sepsis patients with its overexpression associated with multiple organic dysfunctions, elevated Th17 cells, and increased mortality risk, which implies that it could forecast the prognosis of sepsis patients." (PMID 35262976, 2022). "Collectively, these findings provide pharmacological evidence that Emodin targeted BCL‐10 regulates the BCL‐10/MALT1 complex and suppresses NF‐κB activation, ultimately conferring significant multiorgan protective effects in sepsis." (PMID 40779122, 2025). "Emodin targets BCL‐10 to modulate the BCL‐10/MALT1 complex, thereby suppressing NF‐κB activation and significantly exerting multiorgan protective effects in sepsis." (PMID 40779122, 2025). "This study aimed to explore the role of MALT1 in sepsis-induced organ injury, immune cell dysregulation, and inflammatory storms." (PMID 36960276, 2023). "In the current study, MALT1 overexpression promoted macrophage infiltration in the lung, liver, and kidney, as well as the Th17/Treg ratio, while decreasing the Th1/Th2 ratio; however, MALT1 knockdown showed the opposite effect in sepsis model mice." (PMID 36960276, 2023). "The current study aimed to explore the effect of MALT1 on multiple organ injuries, macrophage infiltration and polarization, Th1/Th2 and Th17/Treg imbalance, and its downstream pathway in sepsis." (PMID 36960276, 2023). "In terms of the involvement of MALT1 in sepsis, a recent clinical study revealed that MALT1 is elevated in septic patients, and its high expression is positively correlated with Th1 cells, multiple organ injury, and mortality risk in septic patients." (PMID 36960276, 2023). "Then, the present study disclosed that PBMC MALT1 expression was positively linked with general SOFA score, SOFA respiratory system score, and SOFA liver score in sepsis patients." (PMID 35262976, 2022). "MALT1 expression, Th1 cells, Th17 cells, and IL‐17A elevated in sepsis deaths compared with sepsis survivors." (PMID 35262976, 2022). "Herein, the current study aimed to investigate the correlation of MALT1 with Th1 cells, Th17 cells, and prognosis in sepsis patients." (PMID 35262976, 2022). "PBMC MALT1 expression was elevated in sepsis deaths (3.570 (IQR: 2.100–5.380)) compared with sepsis survivors (2.080 (IQR: 1.500–3.330)) (Z = −2.561, p = 0.010)." (PMID 35262976, 2022). "Herein, the current study aimed to investigate the correlation of peripheral blood mononuclear cell (PBMC) MALT1 with Th1 cells, Th17 cells, and prognosis of sepsis patients." (PMID 35262976, 2022). "Meanwhile, MALT1 promoted the polarization of M1 macrophages, Th2 cells, and Th17 cells in sepsis." (PMID 36960276, 2023).
Sepsis (continued). "The liver injury score was altered by MALT1 modification, indicating that liver injury might come from a second attack of sepsis." (PMID 36960276, 2023). "Conclusively, MALT1 exacerbates multiple organ injury, inflammation, M1 macrophage polarization, and Th1/Th2 and Th17/Treg ratio imbalance by activating the NF-κB pathway in sepsis." (PMID 36960276, 2023). "In terms of the regulation of MALT1 in sepsis, although a recent study revealed its positive correlation with multiple organ injury in patients with sepsis, whether MALT1 exerts a regulatory effect on sepsis-induced organ injury remains unclear." (PMID 36960276, 2023). "Furthermore, the ROC curve presented that PBMC MALT1 exhibited a good ability in discriminating sepsis patients from HCs with area under curve (AUC) of 0.861 (95% confidence interval (CI): 0.796–0.927)." (PMID 35262976, 2022). "However, the clinical relevance of MALT1 with sepsis, which is one of the most serious infection‐related diseases, still remains elusive." (PMID 35262976, 2022). "MALT1 expression was higher in sepsis patients than HCs (p < 0.001)." (PMID 35262976, 2022). "In the current study, PBMC MALT1 expression was positively associated with Th17 cells, IL‐17A level in sepsis patients, but not with Th1 cells or IFN‐γ level." (PMID 35262976, 2022). "However, the regulation of MALT1 in the pathogenesis and progression of sepsis is still unclear." (PMID 36960276, 2023). "Moreover, MALT1 exerted these effects by activating the NF-κB pathway in sepsis." (PMID 36960276, 2023). "However, the interaction between MALT1 and the NF-κB pathway in sepsis has yet to be elucidated." (PMID 36960276, 2023). "Correspondingly, MALT1 overexpression might be correlated with sepsis severity in sepsis patients." (PMID 35262976, 2022). "Eight genes (CLEC5A, MALT1, NAIP, NLRC4, SERPINB1, SIRT1, STAT3, and TLR2) related to sepsis diagnosis were screened by multiple machine learning algorithms." (PMID 36817458, 2023). "Third, the target organ of MALT1 that induces the pathogenesis and progression of sepsis was not explored, which should be further verified with conditioned MALT1 modification in a septic mouse model." (PMID 36960276, 2023). "The median PBMC MALT1 expression in sepsis patients and HCs was 2.395 (interquartile range (IQR): 1.640–3.675) and 0.980 (IQR: 0.763–1.450), separately, which showed that PBMC MALT1 expression was higher in sepsis patients compared with HCs (Z = −6.410, p < 0.001)." (PMID 35262976, 2022). "MALT1 expression was positively correlated with Th17 cells (rs = 0.291, p = 0.038) and IL‐17A (rs = 0.383, p = 0.001), but not with Th1 cells (rs = 0.204, p = 0.151) or IFN‐γ (rs = 0.175, p = 0.125) in sepsis patients." (PMID 35262976, 2022). "Additionally, in terms of these indexes in discriminating sepsis deaths from sepsis survivors, PBMC MALT1 disclosed a similar value as Th1 cells, IFN‐γ, Th17 cells, and IL‐17A did, while these values were numerically inferior to APACHE II score and SOFA score." (PMID 35262976, 2022). "MALT1 expression (p = 0.010), Th1 cells (p = 0.010), Th17 cells (p = 0.038), and IL‐17A (p = 0.012), except for IFN‐γ (p = 0.102), elevated in sepsis deaths compared with sepsis survivors." (PMID 35262976, 2022). "According to previous studies, MALT1 is able to regulate the polarization of macrophages and CD4+ T cells; however, whether similar regulatory effects also exist under sepsis conditions is still unclear." (PMID 36960276, 2023). "However, previous studies never evaluate the correlation of MALT1 expression with this index in sepsis." (PMID 35262976, 2022). "Additionally, it is illustrated that MALT1 enhances the differentiation of CD4+ T cells into Th1 and Th17 cells, meanwhile the differentiation of CD4+ T cells into Th1 and Th17, which are important in the pathology of sepsis." (PMID 35262976, 2022). "MALT1 expression was positively correlated with Th17 cells and IL‐17A, but not with Th1 cells or IFN‐γ in sepsis patients." (PMID 35262976, 2022).
cholangiocarcinoma (5 papers, 2017 to 2026). A carcinoma that arises from the intrahepatic biliary tree (intrahepatic cholangiocarcinoma) or from the junction, or adjacent to the junction, of the right and left hepatic ducts (hilar cholangiocarcinoma). "A previous study concluded that cholangiocarcinoma patients with higher MALT1 expression exhibited poorer survival rates compared to those with lower MALT1 expression." (PMID 33802402, 2021).
Crohn disease (5 papers, 2011 to 2023). A gastrointestinal disorder characterized by chronic inflammation involving all layers of the intestinal wall, noncaseating granulomas affecting the intestinal wall and regional lymph nodes, and transmural fibrosis. "Furthermore, MALT1 was positively related to C‐reactive protein (CRP), TNF‐α, IL‐17A, and mayo score in A‐UC patients; positively correlated with CRP, erythrocyte sedimentation rate, TNF‐α, and Crohn's disease activity index score in A‐CD patients." (PMID 34997981, 2022).
inflammatory bowel disease (5 papers, 2014 to 2022). A spectrum of small and large bowel inflammatory diseases of unknown etiology. "However, clinical involvement of MALT1 in inflammatory bowel disease (IBD) patients remains unclear." (PMID 34997981, 2022). "Taken together, our results demonstrated that inhibition of the protease activity of MALT1 might be a viable strategy to treat inflammatory bowel disease and the NLRP3 inflammasome and NF-κB activation are critical components in MALT1 signaling cascades in this disease model." (PMID 27105502, 2016).
peanut allergy (5 papers, 2021 to 2025). "What is more, MALT1 and rs57265082 (MALT1 SNP) were associated with the development of peanut allergy in individuals who avoided peanuts in the LEAP study." (PMID 41153664, 2025). "This research team previously associated the MALT1 SNP rs57265082, a paracaspase-encoding gene, with peanut allergy in the avoidance arm of LEAP." (PMID 34981779, 2022). "For example, subsequent whole genome sequencing from the LEAP trial revealed a novel association for peanut allergy with a single nucleotide variant in the mucosa-associated lymphoid tissue lymphoma translocation (MALT1) gene." (PMID 34616405, 2021). "In addition, the aberrant expression of the MALT1 gene, implicated as an independent risk factor for peanut allergy, added authenticity to our study." (PMID 36496569, 2022). "Nevertheless, deeper investigation for better understanding the role of MALT1 signaling in peanut allergy is warranted." (PMID 34981779, 2022). "Thus, the role of MALT1 allele in peanut allergy pathogenesis is likely independent of allergen-epitope presentation." (PMID 34981779, 2022). "Also, MALT1 has not been identified as a risk allele in peanut allergy in general population GWAS." (PMID 34981779, 2022).
ankylosing spondylitis (4 papers, 2022 to 2024). An autoimmune chronic inflammatory disorder characterized by inflammation in the vertebral joints of the spine and sacroiliac joints. "This study aimed to explore the relation between MALT1 and treatment efficacy to tumor necrosis factor inhibitor (TNFi) in ankylosing spondylitis (AS) patients." (PMID 35622982, 2022). "Mucosa‐associated lymphoid tissue lymphoma translocation protein 1 (MALT1) expression in 73 ankylosing spondylitis (AS) patients was detected at Week (W) 0, W4, W8, and W12 after treatment initiation by RT‐qPCR." (PMID 35622982, 2022). "A previous study found that MALT1 was positively correlated with Th17 cells, and inflammation and its decrement, along with treatment, reflects the response to TNF inhibitor in ankylosing spondylitis patients." (PMID 38978626, 2024).
atherosclerosis (4 papers, 2021 to 2024). A disease characterized by the build-up of fatty material and calcium deposition in the arterial wall resulting in partial or complete occlusion of the arterial lumen. "In conclusion, our results demonstrate that MALT1 inhibition in vascular SMCs leads to ferroptosis resulting in loss of contractility, inhibition of neointima formation, and decrease of atherosclerosis." (PMID 38097554, 2023).
tuberculosis (4 papers, 2011 to 2023). A chronic, recurrent infection caused by the bacterium Mycobacterium tuberculosis. "‘Tuberculosis’ KEGG pathway map comprised five signal transduction mediators, Irak2, Jak2, Malt1, Ripk2, and Src, regulated by induced enhancers." (PMID 30669987, 2019).
dermatitis (3 papers, 2018 to 2022). An inflammatory process affecting the skin. "Malt1-KO mice are known to have a defect in Treg development, which could be responsible for the skin inflammation in aging MALT1-deficient mice." (PMID 31632405, 2019). "Malt1-KO mice that develop skin inflammation were found to have increased serum levels of the pro-inflammatory cytokines IL-2, IL-4, IL-6, IL-17, IFN-γ, and TNF." (PMID 31632405, 2019). "Our present finding that Malt1-KO mice spontaneously develop skin inflammation upon aging, implicates a role for MALT1-independent antigen or cytokine receptor signaling leading to low or intermediate T cell activation." (PMID 31632405, 2019). "However, in the present paper we show that Malt1-KO mice develop atopic-like dermatitis upon aging." (PMID 31632405, 2019). "However, our T cell-specific Malt1-KO mice did not develop skin lesions, suggesting that absence of MALT1 in T cells only is not sufficient to drive skin inflammation in aging mice." (PMID 31632405, 2019).
hepatocellular carcinoma (3 papers, 2016 to 2023). A malignant tumor that arises from hepatocytes. "Likewise, TIFA (TNF receptor associated factor-interacting protein with a forkhead-associated domain), which can sensitize hepatocellular carcinoma (HCC) cells to apoptosis, competes with MALT1 for TRAF6 binding." (PMID 35203553, 2022).
osteoarthritis (3 papers, 2022 to 2024). A noninflammatory degenerative joint disease occurring chiefly in older persons, characterized by degeneration of the articular cartilage, hypertrophy of bone at the margins and changes in the synovial membrane. "In conclusion, this is the first study that establishes the role of MALT1-LPCAT3 in the development of osteoarthritis." (PMID 38519981, 2024). "Overall, our data reveal a previously unrecognized role of the MALT1-LPCAT3 axis in osteoarthritis." (PMID 38519981, 2024). "Besides, MALT1 expressions in 20 osteoarthritis patients and 20 healthy controls (HCs) were also detected." (PMID 35622982, 2022). "MALT1 expression was higher in AS patients compared with HCs and osteoarthritis patients." (PMID 35622982, 2022). "MALT1 was increased in RA patients compared to osteoarthritis patients and healthy controls." (PMID 35967391, 2022). "PBMC MALT1 in 30 osteoarthritis patients and 30 health controls were also detected." (PMID 35967391, 2022). "This is the first study to describe the role of the MALT-LPCAT3 axis in the development of osteoarthritis.Our data supports that targeting the MALT1-LPCAT3 axis using MALT1 inhibitors or LPCAT3 siRNA-liposomes may become attractive therapies for the treatment of OA." (PMID 38519981, 2024). "Besides, 20 osteoarthritis patients and 20 healthy controls (HCs) were enrolled to detect MALT1." (PMID 35622982, 2022). "This is the first study that establishes the role of MALT1-LPCAT3 axis in the development of osteoarthritis and provides novel therapeutic avenues targeting this pathway using LPCAT3 siRNA-lipid nanoparticle approach or local injections of MALT1-inhibitors for the treatment of OA." (PMID 38519981, 2024).